HS3ST2 (heparan sulfate-glucosamine 3-sulfotransferase 2)
Description:
Sulfotransferase that utilizes 3'-phospho-5'-adenylyl sulfate (PAPS) to catalyze the transfer of a sulfo group to an N-unsubstituted glucosamine linked to a 2-O-sulfo iduronic acid unit on heparan sulfate. Catalyzes the O-sulfation of glucosamine in GlcA2S-GlcNS. Unlike HS3ST1/3-OST-1, does not convert non-anticoagulant heparan sulfate to anticoagulant heparan sulfate.
Synonyms: 3OST2; 30ST2
Tractability: Antibody: UniProt predicts a signal peptide or a membrane-spanning region.
Gene: Protein-coding gene on chromosome 16 (22,814,162 to 22,916,338, forward strand). Ensembl gene ENSG00000122254.
Subcellular location: Golgi apparatus membrane
Pathways (Reactome):
Metabolism: HS-GAG biosynthesis
Gene Ontology:
Molecular function: [heparan sulfate]-glucosamine 3-sulfotransferase activity; sulfotransferase activity
Biological process: glycosaminoglycan biosynthetic process; heparan sulfate proteoglycan biosynthetic process
Cellular component: Golgi membrane; membrane
Genetic constraint (gnomAD): Loss-of-function variants: 18 observed, 27.84 expected, observed/expected ratio (o/e) 0.65, 90% interval 0.45 to 0.96. The upper end of that interval is the gene's LOEUF score, 0.96, which puts it in group 4 of 6, group 1 being the genes least tolerant of losing a copy. Missense variants: 402 observed, 493.06 expected, observed/expected ratio (o/e) 0.82, 90% interval 0.75 to 0.88. Synonymous variants: 237 observed, 217.65 expected, observed/expected ratio (o/e) 1.09, 90% interval 0.98 to 1.21.
Homologues: Orthologues: chimpanzee HS3ST2 (100% identical), macaque HS3ST2 (99% identical), guinea pig HS3ST2 (98% identical), rabbit HS3ST2 (97% identical), pig HS3ST2 (96% identical), mouse Hs3st2 (96% identical), rat Hs3st2 (96% identical), dog HS3ST2 (93% identical), zebrafish hs3st2 (70% identical), tropical clawed frog hs3st2 (66% identical), Drosophila melanogaster sfl (28% identical), Caenorhabditis elegans hst-1 (25% identical). Paralogues in human: HS3ST4 (64% identical), HS3ST3A1 (59% identical), HS3ST3B1 (59% identical), HS3ST6 (53% identical), HS3ST5 (35% identical), HS3ST1 (33% identical), NDST2 (32% identical), NDST4 (32% identical), NDST1 (32% identical), NDST3 (31% identical).
Diseases named in the same sentence as HS3ST2 in open-access papers:
HS3ST2 is named in the same sentence as 34 diseases in open-access papers, as found by Europe PMC text mining. Sharing a sentence is not in itself a finding about the gene and the disease. The quoted sentences say what the papers report.
breast carcinoma (9 papers, 2016 to 2024). "Genes SIAH2, CDH5 and HS3ST2 were reported to be associated with breast cancer." (PMID 31640538, 2019). "Overexpression of HS3ST2 can increase the proliferation and colony-forming units of the BT-20 breast cancer cell line by enhancing the expression of anti-apoptotic molecules including survivin and XIAP." (PMID 36836593, 2023). "We studied the influence of HS2ST1 and HS3ST2 overexpression on the CSC phenotype in breast cancer cell lines representative of the triple-negative (MDA-MB-231) and hormone-receptor positive subtype (MCF-7)." (PMID 33102470, 2020). "Our results furthermore show that the overexpression of HS2ST1 and HS3ST2 significantly alters several CSC-related characteristics in breast cancer cells in general, which is worthy of future evaluation in more complex in vivo systems." (PMID 33102470, 2020). "Previous studies demonstrated an important role of HS3ST2 and HS2ST1 and the associated changes in HS structure in modulating receptor tyrosine kinase dependent signaling and breast cancer cell invasion, proliferation and senescence." (PMID 33102470, 2020). "HS3ST2 overexpression increases the viability and invasiveness of the breast cancer MDA-MB-231 cells." (PMID 30360368, 2018). "We recently demonstrated that transient overexpression of HS3ST2, 3B or 4 enhanced the proliferation of breast cancer MDA-MB-231 cells and promote efficient protection against pro-apoptotic stimuli." (PMID 30360368, 2018). "To explore the molecular mechanisms responsible for the functional impact of HS3ST2, 3B and 4, we analysed the principal signaling pathways that regulates breast cancer cell growth, invasiveness and survival." (PMID 29547633, 2018). "In conclusion, we demonstrated that overexpression of HS3ST2, 3B and 4 enhanced proliferation and survival of the breast cancer MDA-MB-231 cells." (PMID 29547633, 2018). "HS3ST2 overexpression, on the other hand, has breast cancer cell-type-dependent effects on invasion and proliferation, affects stemness-associated signaling pathways and protects breast cancer cells against apoptosis and natural killer cell-mediated cell death." (PMID 33102470, 2020). "Moreover, HS3ST2 gene hypermethylation was detected in the majority of primary breast cancer samples analysed, and also in human colon, lung and pancreatic cancers." (PMID 31249810, 2019). "Overall, we found that HS3ST2, 3B and 4 enhance cell proliferation and promote efficient protection against cell death, which suggests that the three isozymes may display a prominent role in breast cancer progression." (PMID 29547633, 2018). "Five of these genes were found to be significantly methylated in breast cancers from our cohort in Senegal (APC, RASSF1, GASTP1, SCGB3a1, and HS3ST2)." (PMID 31819783, 2019). "Then, they demonstrated that HS3ST2 was not expressed in cell lines representative of the different molecular breast cancer subgroups." (PMID 31249810, 2019). "In line with these last findings, we recently demonstrated that transient expression of HS3ST2, 3B and 4 enhances the proliferation of MDA-MB-231 cells and promotes efficient protection against cell death, which suggests that these isozymes may display a prominent role in breast cancer expansion." (PMID 30360368, 2018).
lung carcinoma (7 papers, 2013 to 2024). "Exogenous expression of HS3ST2 in lung cancer cells H460 and H23 inhibited cell migration, invasion, cell proliferation and whereas knockdown of HS3ST2 in NHBE cells induced cell migration, invasion, and cell proliferation invitro." (PMID 24265783, 2013). "HS3ST2 hypermethylation was characterized in six lung cancer cell lines, and its clinical significance was analyzed using 298 formalin-fixed paraffin-embedded tissues and 26 fresh-frozen tissues from 324 NSCLC patients." (PMID 24265783, 2013). "HS3ST2 mRNA levels were substantially lower in six lung cancer cell lines than in two bronchial epithelial cell lines (black bar)." (PMID 24265783, 2013). "Furthermore, certain methylation markers, such as DAL-1, EPHB6, HS3ST2, TMEM88 and MGMT, specifically associated with lung cancer progression and metastasis, were found to have increased methylation levels." (PMID 37506102, 2023). "HS3ST2 protein expression could be used as a favorable prognostic tissue biomarker in patients with primary advanced-stage lung cancer." (PMID 34315491, 2021). "HS3ST2 hypermethylation has recently been reported in a variety of cancers, such as breast cancer, colorectal cancer, gastric cancer, hematological neoplasm, lung cancer, pancreatic cancer, prostate cancer, and cervical cancer." (PMID 24265783, 2013). "To investigate if downregulation of HS3ST2 is dependent on hypermethylation of the gene, we analyzed the re-expression and demethylation of silenced HS3ST2 by qRT-PCR and EpiTYPERTM assay after treatment of lung cancer cells with 10 μM 5-Aza-dC for 72 h." (PMID 24265783, 2013). "However, the clinicopathological significance of HS3ST2 hypermethylation remains elusive in lung cancer." (PMID 24265783, 2013).
colon cancer (2 papers, 2010 to 2013). "Methylation-associated silencing of HS3ST2 expression has been demonstrated in breast, lung, pancreatic and colon cancers." (PMID 20492682, 2010). "Among the group of the most consistently hypermethylated genes in both human colon cancer and mouse intestinal adenoma (48 genes), we found Cdh4, Crabp1, Crmp1, Dbc1, Duox1, Grm7, Hand1, Hs3st2, Pcdh17 and Pdpn, which have previously been suggested as cancer biomarkers." (PMID 23408899, 2013).
prostate carcinoma (2 papers, 2013 to 2021). A carcinoma that arises from epithelial cells of the prostate gland. "In breast, colorectal, lung, cervical, pancreatic and recurrent prostate cancers, HS3ST2 is silenced due to hypermethylation, suggesting that it may play an important role in multiple cancers." (PMID 34315491, 2021). "HS3ST2 also shows high methylation in prostate cancer with recurrence." (PMID 24265783, 2013).
tauopathy (2 papers, 2022 to 2025). Neurodegenerative disorders involving deposition of abnormal tau protein isoforms (tau proteins) in neurons and glial cells in the brain. "A previous study showed that knockdown of Hs3st2 in a zebrafish model of tauopathy expressing hTauP301L significantly reduced the level of phosphorylated tau in both the brain and the spinal cord and subsequently recovered the axonal length of motor neurons." (PMID 39920775, 2025). "Previously, we showed in cell models of tauopathy that HS3ST2 critically participates to the abnormal phosphorylation of tau28." (PMID 35760982, 2022). "Previously, we showed that the neural heparan sulfate 3-O-sulfotransferase HS3ST2 is critical for the abnormal phosphorylation of tau in Alzheimer's disease-related tauopathy." (PMID 35760982, 2022).
bladder cancers (1 paper, 2017). "Similar patterns of hypermethylation of HS3ST2 and increased tumor invasiveness have also been observed in lung and bladder cancers indicating substantial tumor suppressive properties associated with proper HS3ST2 function and HS chain sulfation." (PMID 28672878, 2017).
cholangiocarcinoma (1 paper, 2020). A carcinoma that arises from the intrahepatic biliary tree (intrahepatic cholangiocarcinoma) or from the junction, or adjacent to the junction, of the right and left hepatic ducts (hilar cholangiocarcinoma). "In contrast, mononuclear phagocytes exhibited up‐regulation of chemokines such as CCL4, CCL4L2, and CCL3L3 in the cholangiocarcinoma samples and extracellular remodeling genes such as MMP19, MMP12, and HS3ST2 in the metastatic patients." (PMID 33332768, 2020).
diabetes (1 paper, 2011). "Our microarray analysis revealed that phloridzin specifically reversed the effect of diabetes on the expression of 2 enzymes involved in the regulation of glucosamine, heparan sulfate (glucosamine) 3-O-sulfotransferase 2 and 5 (respectively Hs3st2 and Hs3st5)." (PMID 22046295, 2011).
ductal carcinoma in situ of (1 paper, 2013). "HS3ST2 hypermethylation was found at a high frequency in ductal carcinoma in situ of breast and in cytology specimens of cervical intraepithelial neoplasia 3 (CIN3), suggesting HS3ST2 hypermethylation probably occurs early during malignant transformation of the breast and cervix." (PMID 24265783, 2013).
Granuloma (1 paper, 2021). A compact, organized collection of mature mononuclear phagocytes, which may be but is not necessarily accompanied by accessory features such as necrosis. "Considering the functional evidence for HS3ST2, it is possible that this gene may be involved with granuloma disassembly, tissue permeability, and cellular migration in leprosy, which would explain its overexpression in MB lesions." (PMID 34695167, 2021).
leprosy (1 paper, 2021). Leprosy is a chronic infectious disease affecting primarily the skin and peripheral nervous system. "The HS3ST2 gene was consistently more expressed in MB leprosy lesions compared to PB, whereas the opposite was observed for CD40LG and CCR6." (PMID 34695167, 2021).
lymph node metastasis (1 paper, 2021). "The expression of hsa-miR-99a and hsa-miR-100 decreased significantly in CRC tissue with lymph node metastasis compared to CRC tissue without lymph node metastasis (P < 0.01, P < 0.05), while the expression of HS3ST2 greatly increased in CRC tissue with lymph node metastasis (P < 0.05)." (PMID 34315491, 2021). "Moreover, the expression of hsa-miR-99a, hsa-miR-100, and HS3ST2 was validated by qPCR using 20 CRC tissue samples with lymph node metastasis and 20 CRC tissue samples without lymph node metastasis." (PMID 34315491, 2021).
myeloid malignancies (1 paper, 2009). "As well as genes predominantly methylated in certain HN subtypes, we also identified six genes, i.e. DBC1, DIO3, FZD9, HS3ST2, MOS and MYOD1, that were significantly hypermethylated in B-cell, T-cell and myeloid malignancies." (PMID 19750229, 2009). "As well as identifying genes showing aberrant DNA methylation in certain HN subtypes, we also detected six genes—DBC1, DIO3, FZD9, HS3ST2, MOS, and MYOD1—that were significantly hypermethylated in B-cell, T-cell, and myeloid malignancies." (PMID 19750229, 2009).
tumor (16 papers, 2008 to 2025). "Analytical results revealed TYMP and HS3ST2 in tumor samples were significantly upregulated and GCNT4 and FUT3 were significantly downregulated." (PMID 41155476, 2025). "A body of evidence has accumulated over the past two decades indicating that HS3ST2 is epigenetically silenced in a wide range of cancers and tumor cell lines." (PMID 31249810, 2019). "On the one hand, aberrant methylation of the genes encoding HS3ST2 and HS3ST3A was described in various cancers and tumor cells, and reversing methylation restored their expression and resulted in the suppression of tumor cell growth." (PMID 30360368, 2018). "Finally, they selected three of these markers (the genes HS3ST2, SLIT2 and SEPTIN9) for combination with the FGFR3 mutations in a logistic regression model, obtaining a sensitivity of 94.5% (96% in high-grade tumours) and a specificity of 75.9%." (PMID 32664878, 2020). "A conflicting literature has recently reported that HS3ST2, 3A, 3B and 4 may exhibit either tumor-promoting or anti-oncogenic properties, depending on the model used and cancer cell phenotype." (PMID 29547633, 2018). "A conflicting literature has however suggested that high expression of HS3ST2 and 3A may result in the suppression of tumor cell growth." (PMID 29547633, 2018). "HS3ST2 mRNA levels were significantly higher in normal tissues than in tumor tissues (P = 0.0004, Wilcoxon signed-rank test), and negative correlation was observed between expression and methylation of the HS3ST2 in 26 tumor tissues (ρ = -0.51, P = 0.009, Spearnman’s rank correlation)." (PMID 24265783, 2013). "Taken together, five tumor antigens (ALOX15B, HS3ST2, PIGR, ZMYND15, and LIMK1), with potentially provocative effects on immunological functions, were identified and considered as eligible candidates for anti-PRCC mRNA vaccine development." (PMID 36836593, 2023). "Five tumor antigens, including ALOX15B, HS3ST2, PIGR, ZMYND15 and LIMK1, were identified for PRCC, which were correlated with patients’ prognoses and infiltration levels of APCs." (PMID 36836593, 2023). "After that, five tumor antigens (ALOX15B, HS3ST2, PIGR, ZMYND15, and LIMK1) were identified to be candidates for the mRNA-based vaccine development, all of which were correlated with survival time of PRCC patients and the degree of APC infiltration." (PMID 36836593, 2023). "We focused in those genes that were significantly differently methylated in the basal-like tumor subtype (HOXA9, SOX1, VAMP8, and TNFRS10D) and those that were significantly hypermethylated in the luminal B tumors (NPY, RASSF1, HS3ST2, DBC1, FGF2, CD40." (PMID 20920229, 2010). "DNA methylation at the promoter region of the MGMT, CDKN2A, SFRP1, TMEFF2, HS3ST2 (3OST2), RASSF1A and GATA4 genes was evaluated by quantitative methylation specific PCR in both tumor and corresponding normal appearing colorectal mucosa samples." (PMID 20098741, 2010). "However, the situation is not so clear, and there is accumulating evidence that HS3ST2, HS3ST3A, HS3ST3B, and HS3ST4 may also act as tumor-promoting enzymes in a number of cancer cells depending on their phenotypes and molecular signatures." (PMID 31249810, 2019).
cancer (15 papers, 2009 to 2025). A tumor composed of atypical neoplastic, often pleomorphic cells that invade other tissues. "Hypermethylation of the genes encoding HS3ST2 has been described in certain cancer cells, resulting in a loss of its expression." (PMID 29547633, 2018). "HS3ST2 (heparan sulfate-glucosamine 3-sulfotransferase 2) encodes an enzyme that participates in cell proliferation, apoptosis, autophagy, and other processes associated with cancer." (PMID 32581649, 2020). "TK1, TCN1, CAV1, and HS3ST2 play indispensable roles in survival predictions and pathogenesis of various cancers." (PMID 35898471, 2022). "As a consequence, the expression level of HS3ST2 was markedly reduced in the cancer sample compared with the matched normal counterpart." (PMID 31249810, 2019). "In our hands, overexpression of HS3ST2 resulted in a significant increase in the growth of both cancer cell lines." (PMID 29547633, 2018). "Aberrant methylation of the genes encoding HS3ST2 and HS3ST3A was indeed described in various cancers." (PMID 29547633, 2018). "We also showed that HS3ST3B and HS3ST4 shared with HS3ST2 the same promoting effects, which revealed that the expression of these isozymes had similar functional impact on cancer cell behavior." (PMID 30360368, 2018). "Hyper-methylation of the genes encoding HS3ST2 and HS3ST3A was described in a number of cancer cells." (PMID 30360368, 2018). "It has therefore been concluded that HS3ST2 methylation may act as a novel cancer-related molecular mechanism for the detection of new treatment strategies." (PMID 34315491, 2021). "The prognostic significance of HS3ST2 mRNA expression in several cancer types has been evaluated." (PMID 34315491, 2021). "In the aging model group, the genes that were highly expressed were mainly FOSB, HS3ST2, and FSTL4, and other genes related to tumors, cancer, and other diseases." (PMID 38191526, 2024). "In accordance with this assumption, a number of studies have documented the epigenetic repression of HS3ST2 and HS3ST3A in many cancers." (PMID 31249810, 2019). "However, in the aging model group, the genes that were highly expressed were mainly FOSB, HS3ST2, and FSTL4, which are related to tumors, cancer, and other diseases." (PMID 38191526, 2024).
gastrointestinal tumors (1 paper, 2010). "Of the top 10 genes that were hypermethylated in CIMP-H compared to CIMP-L tumors, 5 have previously been implicated in the pathogenesis of gastrointestinal tumors (NTRK3, HS3ST2, TWIST1, CD40 and EYA4)." (PMID 20492682, 2010).
HS3ST2 also shares sentences with these, for which no sentence is quoted: gastric cancer (4 papers); Alzheimer disease (3); colorectal cancer (2); glioblastoma (2); glioma (2); hepatocellular carcinoma (2); pancreatic cancers (2); anaplastic astrocytoma (1); astrocytoma (1); B-cell lymphomas (1); chronic kidney disease (1); endometrial cancer (1); invasive breast ductal carcinomas (1); lymphoma (1); non-small cell lung carcinoma (1); oral cancer (1); ovarian carcinoma (1); T-cell lymphomas (1).